SOX9 (SRY-box transcription factor 9)
Diseases named in the same sentence as SOX9 in open-access papers (continued):
Sharing a sentence is not in itself a finding about the gene and the disease.
prostate carcinoma (continued). "This work defines a novel permissive role for Sox9 in cancer initiation and suggests that manipulation of Sox9 targets in at-risk men may prove useful in the chemoprevention of prostate cancer." (PMID 22761195, 2012). "In vitro and in vivo studies have shown that suppression of SOX9 inhibits proliferation of stomach, lung, and prostate cancer cells." (PMID 38956258, 2024). "Consistently, SOX9 overexpression promotes the development of invasive carcinoma, suggesting a distinct role of SOX9 in prostate cancer." (PMID 37821954, 2023). "The regulation of SOX9 expression by the adenosine analog CD has also been studied in cancer cells, including prostate cancer cell lines." (PMID 37020558, 2023). "Sox9 has also been expressed in prostate cancer cell subsets and increased in recurrent hormone-refractory prostate cancer (PCa)." (PMID 35627101, 2022). "Evidence showed that the WNT/β-catenin signaling is activated in prostate cancer cells, especially those with SOX9 overexpression, indicating that prostate cancer patients with high SOX9 levels are more sensitive to WNT pathway antagonists." (PMID 35267473, 2022). "SOX9 has been identified as an oncogene, and its high expression is closely related to the occurrence of prostate cancer." (PMID 33794893, 2021). "The overexpression of SOX9 was reported in some types of malignancies such as metastatic melanoma non-small cell lung cancer, prostate cancer, and esophageal squamous cell carcinoma." (PMID 33736633, 2021). "Of note was PI3K family members: PIK3C2G, PIK3CA, PIK3CB, PIK3R4, Mucin family members: MUC1, MUC4 and MUC6 and other prostate cancer associated genes such as SMAD4, SOX9 and SPOP7,9,40,41." (PMID 32796921, 2020). "SOX9 drives prostate cancer development through various mechanisms, particularly related to WNT/β-catenin signaling activation." (PMID 31366128, 2019). "Previous studies observed that this compound blocked the expression and transcriptional activity of hypoxia-induced factor-1α in human prostate cancer cells and inhibited expression of Gata7 and Sox9 transcription factors in rat cardiomyocytes." (PMID 31905721, 2019). "In conclusion, we identified a novel role of SOX9 as a driver of invasive prostate cancer, a property of aggressive disease." (PMID 29484136, 2018). "Here we have identified a novel role for the transcription factor, SOX9, as a driver of aggressive invasive prostate cancer." (PMID 29484136, 2018). "Analyses of genetically modified mice show that overexpression of Sox9 in the prostate of mice with a homozygous Pten deletion leads to highly invasive prostate cancer and metastasis." (PMID 29484136, 2018). "Our study has identified a novel driver of prostate cancer progression and highlighted the cellular and molecular processes that are regulated by Sox9 to achieve invasive disease." (PMID 29484136, 2018). "In an effort to determine the role of SOX9 in aggressive prostate cancer we generated genetically modified mice that express extra levels of Sox9 in prostate epithelia in addition to a homozygous Pten deletion." (PMID 29484136, 2018). "Castration is the first line of therapy for prostate cancer patients in the clinic and SOX9 has been proposed to interact with AR." (PMID 29484136, 2018). "This study identifies a novel role for SOX9 as a driver of aggressive late stage invasive prostate cancer in homozygous Pten mutant animals." (PMID 29484136, 2018). "We can explain this result by SOX9's ability to enhance prostate cancer (PCa) tumor growth, promote tumor cell proliferation, invasion and metastasis." (PMID 29348895, 2017). "During tumor progression in a murine model of prostate cancer, there was an increase in EMT-associated Sox9 expression and changes in the Wnt/β-catenin signaling pathway." (PMID 29162839, 2017).
prostate carcinoma (continued). "Increased SOX9 expression drives prostate cancer (PCa) tumor growth and angiogenesis and promotes prostate cancer invasion by reactivating the WNT/β-catenin signaling that mediates ductal morphogenesis in fetal prostate." (PMID 29348895, 2017). "Sox9 is required for the early differentiation of the prostate bud epithelia, and fully involved in the carcinogenesis, differentiation, and invasion prostate cancer through reactivating the WNT/beta-catenin signaling that mediates ductal morphogenesis." (PMID 27589569, 2016). "We aimed to evaluate ERG and SOX9 as potential biomarkers of docetaxel response in metastatic castration-resistant prostate cancer (mCRPC) patients." (PMID 27863438, 2016). "In order to confirm the microarray results, we tested by qRT-PCR the effect of CCG-1423 on levels of RGS4, RGS7, CTGF, and SOX9 mRNA in PC-3 prostate cancer cells." (PMID 27600078, 2016). "In order to better understand the timing of CCG-1423-regulated gene expression, we studied the effect of CCG-1423 on RGS4, RGS7, CTGF, and SOX9 gene expression in PC-3 prostate cancer cells from 1 to 24 h." (PMID 27600078, 2016). "The promising findings of these studies obtained in limited patient sets prompted us to further evaluate the possible clinical impact of SOX9 in prostate cancer." (PMID 26030748, 2015). "In summary, the results of our study demonstrate that SOX9 is expressed in a large fraction of prostate cancers, but has a variable prognostic impact depending of the molecular environment." (PMID 26030748, 2015). "For example, SOX9 is increased in relapsed hormone-refractory prostate cancer, and overexpression of SOX9 enhanced the growth, angiogenesis, and invasion of prostate cancer cells." (PMID 26384302, 2015). "The molecular database attached to our prostate cancer TMA enabled an evaluation of the relationship between SOX9 expression and other key molecular features of prostate cancer." (PMID 26030748, 2015). "A functional relationship of PTEN and SOX9 is indeed supported by two studies using prostate cancer mouse models." (PMID 26030748, 2015). "The results of our study show that a clinical relevance of SOX9 expression levels exists in prostate cancer that greatly depends on the molecular context of the tumor cells." (PMID 26030748, 2015). "The block contains six enhancer elements, of which the E1 enhancer forms a long-range chromatin loop to SOX9 in a prostate cancer cell line." (PMID 24023777, 2013). "In mPIN lesions, we detected high levels of Sox9 expression that declined as invasive tumors developed which mimicked our observations in human prostate cancer cases." (PMID 22761195, 2012). "In the TRAMP model, which recapitulates multiple phases of prostate cancer, we found Sox9 expression highest in mPIN lesions a finding that parallels our previous observation in human prostate lesions." (PMID 22761195, 2012). "Lastly, the abrogation of Sox9 from adult prostate tissue in two genetic models of prostate cancer results in a complete block of carcinogenesis." (PMID 22761195, 2012). "The same report showed that Sox9 is regulated by β-catenin and affects prostate cancer cell proliferation, angiogenesis and invasion; in particular in the LNCaP cell line." (PMID 20500816, 2010). "Furthermore, GATA2-mediated increased chromatin accessibility facilitated the binding of other TFs, including androgen receptor (AR) and SRY-Box Transcription Factor 9 (Sox9), to CREs in prostate cancer cell lines." (PMID 40516868, 2025). "Also of interest were several genes associated with prostate cancer metastases including FOXA1, EZH2, SCHLAP1, CDH1, SOX4, SOX9, HOXB13, and TGFBR3." (PMID 38067373, 2023). "Recent studies also suggest a role for CAFs in regulating SOX9 expression in prostate cancer." (PMID 36003340, 2022). "Moreover, it was reported that the reduction of SOX9 was correlated with a decrease in the ability of prostate cancer cells to migrate and proliferation." (PMID 33736633, 2021).
prostate carcinoma (continued). "Thus, we further selected the top 100 co-expressed genes of SOX9 from the TCGA prostate cancer database." (PMID 33794893, 2021). "However, hypomethylation in the SOX9 promoter, which increases SOX9 expression in prostate cancer, has also been reported." (PMID 34098886, 2021). "For instance, SOX9 is very important in the initiation of pancreatic, gastric, and prostate cancer." (PMID 31057614, 2019). "Besides, SOX9 expression in prostate cancer cells was regulated by Wnt/β-catenin signaling, being AR one identified downstream target." (PMID 31057614, 2019). "Similarly, it has been shown that Sox9 positively regulates multiple genes required for Wnt signalling in prostate cancer." (PMID 30622340, 2019). "The overexpression of SOX9 has also been detected in the lymph nodes of prostate cancer xenografts, in which SOX9 was found to enhance cellular growth, angiogenesis and invasion by promoting epithelial cells to expand into mesenchyme cells during fetal prostate development." (PMID 31060551, 2019). "The transcription factors SOX2 and SOX9 are potential drivers of invasive prostate cancer that induce EMT and stemness whereas, Wnt signaling promotes tumor microenvironment in progenitor cells in castration resistant prostate cancer (CRPC) enhancing their resistance to therapy." (PMID 31798767, 2019). "ZBTB7A physically interacts with SOX9 and functionally antagonizes its transcriptional activity on key target genes; ZBTB7A inactivation determines Rib downregulation, bypass of PTEN loss-induced cellular senescence and invasive prostate cancer." (PMID 31366128, 2019). "Here we identify a novel role for SOX9 at later stages of prostate cancer progression." (PMID 29484136, 2018). "Anyway, the association between ETV5 or SOX9 expression level and the presence of AR variants in prostate cancer cells is not clear." (PMID 29069764, 2017). "Analyses of prostate cancer on xenografts and clinical samples both reveal that SOX9 positively regulates multiple WNT pathway genes, including frizzled (FZD), lipoprotein receptor-related protein (LRP) family members, and the downstream β-catenin effector TCF4." (PMID 28279198, 2017). "The successful analysis of more than 7,500 prostate cancers did not—in a general survey on all tumors—reveal relevant associations of an increased SOX9 expression with unfavorable tumor phenotype or poor patient prognosis as suggested by earlier works." (PMID 26030748, 2015). "Additionally, Sox9 is known to be highly expressed and promote tumorigenicity in prostate cancer, colon cancer and glioblastoma." (PMID 25955804, 2015). "The results of our study demonstrate that decreased, and not elevated, SOX9 protein expression is linked to poor prognosis and that this effect is strictly limited to the subset of prostate cancers harboring PTEN deletions." (PMID 26030748, 2015). "In prostate cancer, nuclear SOX9 expression was observed in 67% of 7,565 interpretable cases." (PMID 26030748, 2015). "Sox9 is also required for cancer initiation in the Hi-Myc prostate cancer model." (PMID 22761195, 2012). "How Sox9 expression allows for pathway deregulation in the transition to human prostate cancer remains unclear and is an active focus of our current research." (PMID 22761195, 2012). "Thus in prostate development, the initial androgen induction of Sox9 is through Fgf2 signaling, a growth factor also overexpressed in prostate cancer." (PMID 22761195, 2012). "Prior work suggests Sox9 plays a role in prostate cancer progression." (PMID 22761195, 2012). "Similarly, Sox9 deletion in two genetic models of prostate cancer (TRAMP and Hi-Myc) prevented cancer initiation." (PMID 22761195, 2012). "However, interestingly, SOX9 was found to be upregulated in IGFBP-rP1-transfected prostate cancer cells, while downregulated in IGFBP-rP1 transfected colon cancer cells, indicating the cell lineage specific regulation." (PMID 20977730, 2010).
prostate carcinoma (continued). "Indeed, by knocking down PHF19L, we observed significant induction of multiple genes known to promote changes in cytoskeleton and adhesion, extracellular matrix remodeling, invasion, and metastasis in prostate cancer (including SOX9, SOX4, MMP1, PLAU, EPCAM, CXCR4, LOX, and MET)." (PMID 32155117, 2020). "Therefore, SOX9 expression could be used as biomarkers of the activation of other pathways known to provoke prostate cancer progression and of docetaxel response together with the results of ERG IHC." (PMID 27863438, 2016). "Several lines of evidence exist that SOX9 might also contribute to prostate cancer initiation and progression, including up-regulation during early stages of prostate neoplasia in mouse models, as well as in human prostatic intraepithelial neoplasia (PIN) and prostate cancers." (PMID 26030748, 2015). "Thus Sox9 is necessary for the initiation of prostate cancer in TRAMP mice." (PMID 22761195, 2012). "Given the key role of Sox9 in the initiation of prostate organogenesis and the observation of high Sox9 levels in premalignant prostatic intraepithelial neoplasia (PIN) lesions in human prostate cancers, we investigated whether Sox9 was also integral to prostate cancer initiation." (PMID 22761195, 2012). "Gene-expression profiling of DU145 prostate cancer cells stimulated with HGF revealed induction of a molecular signature associated with stem cells, characterized by up-regulation of CD49b, CD49f, CD44 and SOX9, and down-regulation of CD24 (‘stem-like signature’)." (PMID 22110593, 2011). "Furthermore, we propose new candidate prostate TIC markers (PROM2 and SOX9) as well as potential biomarkers for prostate cancer status and progression that may be related to the TIC phenotype." (PMID 20500816, 2010). "Activation of c-met in prostate cancer cells stimulates the expression of a stem cell program, characterized by upregulation of CD49b, CD49f, CD44, and SOX9, and downregulation of CD24." (PMID 31366128, 2019). "SOX9 also drives prostate cancer development through WNT pathway activation; treatment of SOX9-expressing prostate cancers with a WNT synthesis inhibitor reduces WNT pathway signaling and tumor growth in murine xenograft models." (PMID 31366128, 2019). "For example, we found that the prognostic value of SOX9 and mTOR expression was limited to ERG-positive cancers while the prognostic value of NBS1, SENP145 CD14746 only seen in ERG-negative prostate cancers." (PMID 28515422, 2017). "SOX9 is thus an interesting example for possibly many more genes that may exert either a tumor promoting or a tumor suppressive action depending on the individual molecular scaffold resulting from specific combinations of genomic changes in prostate cancer cells." (PMID 26030748, 2015). "Id4 was either over-expressed or silenced in prostate cancer cell lines DU145 and LNCaP respectively followed by analysis of PTEN, NKX3.1 and Sox9 expression." (PMID 23786676, 2013). "Recently, it has been reported that knockdown of SOX9, another SOX family member, induced cell-cycle arrest at G1 and upregulated p27Kip1 in prostate cancer cells, indicating that SOX9 positively regulates cell-cycle progression though inhibiting p27Kip1." (PMID 18268498, 2008). "To investigate whether SOX9 and KLF5 are drivers of cancer stemness, we overexpressed these two transcription factors in vitro using the prostate cancer cell line 22Rv1 and normal prostatic epithelial cell line RWPE‐1." (PMID 38483933, 2024). "To this end, we first analyzed the GEO data of prostate cancer cells with or without SOX9 silencing (GSE76441)." (PMID 33794893, 2021). "Our analysis further identified the mitotic kinase NEK2 and stem cell transcription factor SOX9 as downstream targets of ALDH1, which might be involved in the development of multi-drug resistance in prostate cancer cells." (PMID 33339129, 2020).
prostate carcinoma (continued). "Conversely, a gradual decrease of SOX9 has been related to a progression to advanced stage, high Gleason grade, and metastatic growth in ERG-positive cancers, and these effects were strictly limited to the subset of prostate cancers harboring PTEN deletions." (PMID 31057614, 2019). "Finally, prostate cancer cell line models in which Id4 was either silenced or over-expressed confirmed that Id4 regulates NKX3.1, Sox9 and PTEN." (PMID 23786676, 2013). "The gene expression of SOX in human prostate cancer tissue compared with non-cancerous revealed the fact that SOX7, SOX9, and SOX10 were associated with advance-stage prostate cancer, whereas SOX7 and SOX9 were identified as prognostic biomarker in prostate cancer." (PMID 30972102, 2019). "In addition, in vitro studies, SOX9 expression is suppressed by androgens in ERG-negative prostate cancer cells, therefore ADT may actually induce SOX9 expression in ERG-negative patients." (PMID 27863438, 2016). "These numbers are in the upper range of earlier immunohistochemistry studies reporting 41–55% SOX9 positive cancers by conventional large section analysis involving up to 36 tumors, or of TMA studies reporting 46–100% SOX9 positivity in up to 387 prostate cancers." (PMID 26030748, 2015). "While there exists no detectable expression in lumina epithelial cells, SOX9 has already been reported as “expressed in primary prostate cancer in vivo, at a higher frequency in recurrent prostate cancer and in prostate cancer cell lines (LNCaP, CWR22, PC3, and DU145)”." (PMID 20805891, 2010). "In contrast to JQ1, ivermectin also downregulated the expression of EMT genes, such as MET, MMP7, and SOX9, and did not induce EMT in prostate cancer." (PMID 36050295, 2022).